WNT5A (Wnt family member 5A)
Diseases named in the same sentence as WNT5A in open-access papers (continued):
Sharing a sentence is not in itself a finding about the gene and the disease.
tumor (continued). "Daple was shown to be highly expressed in GC tumors, correlating with pathological characteristics (depth of gastric wall invasion, frequency of lymph node metastasis, and clinical stage), Wnt5a/b expression, and metastasis in xenograft tumor assays." (PMID 32195251, 2020). "It was reported that autophagy was able to secrete some specific factors, such as interleukin-6, MMP-2, and WNT-5A, which was required for tumor cell invasion." (PMID 33004792, 2020). "In GIST, CTHRC1 appears to activate the Wnt/PCP pathway in a dose-dependent manner, and Wnt5a/PCP-Rho axis determines the tumor invasion-promoting activity of CTHRC1." (PMID 32848510, 2020). "Soluble factors excreted by tumor cells such as Wnt5a and sTGFBR3 are capable of inducing IDO in immune cells." (PMID 33072086, 2020). "In conclusion, we demonstrated that Wnt5a was mainly localized in TAMs of tumor stroma, especially M2-like TAMs." (PMID 32140070, 2020). "Promoter hypomethylation in prostate cancer has also been reported to facilitate aberrant expression of Wnt5a affecting tumor malignancy, and the up-regulation of Wnt signaling by circulating tumor cells (CTCs) in CRPC patients." (PMID 31108832, 2019). "Roarty and Serra demonstrated that TGFbeta regulated the expression of wingless-related protein family Wnt5a in tumor progression and metastasis." (PMID 31885612, 2019). "In response to stressors, tumor cells with knocked down WNT5A do not display this pseudo-senescent phenotype, whereas highly expressed WNT5A tumor cells do, suggesting WNT5A’s role in promoting cancer cell adaptiveness under stress." (PMID 31382613, 2019). "Our previous studies find that active DAAM1 is elevated by the treatment of Wnt5a or type IV collagen and participates in the tumor cell migration and haptotaxis." (PMID 30911286, 2019). "Expression levels the remaining Wnt ligands, including Wnt1, Wnt3, Wnt4, Wnt5A, Wnt8A, Wnt9B, Wnt10A and Wnt16, remained insignificantly different between liver tumors tissues and adjacent non-tumor tissues." (PMID 30814912, 2019). "By doing so, we identified WNT5a, TGFBI, and SERPINE1, all recently associated with the GBM mesenchymal subtype and tumor invasion, as well as GDF-15, also known to be linked to GBM progression and poor prognosis." (PMID 31453379, 2019). "Consistently, compared with the mimics control group, the tumor volume and tumor weight in the miR-876-5p mimics group were significantly reduced, which can be rescued by ectopic expression of WNT5A or MITF." (PMID 31171711, 2019). "The importance of Wnt5a for angiogenesis and lymphangiogenesis has clearly been shown, and in other tumor entities, Wnt5a has been characterized as a motility-promoting factor." (PMID 31344919, 2019). "The Wnt-5a protein is considered to inhibit the canonical signaling pathway and isconsidered a tumor suppressor." (PMID 30624523, 2019). "Increased expression of Wnt5a and Fzd1 and decreased expression of Lef1 and Camk2a were validated in different tumor samples by quantitative PCR." (PMID 30670683, 2019). "In contrast, just a few studies have described the upregulation of cytokines by Wnt5a in tumor cells." (PMID 31510045, 2019). "Previously, we demonstrated involvement of the transcription factor HNF4α in human GC tumours, and the developmental signal mediator, WNT5A, as a prognostic GC biomarker." (PMID 30792535, 2019). "For instance, it has been shown that the Wnt/Ca+ signaling pathway, which is activated by the tumor suppressor WNT5A in the presence of a “frizzled” class receptor, is down-regulated in several types of cancer." (PMID 30744164, 2019). "The tumor-promoting activities of Wnt5a affect multiple cellular processes, including proliferation, differentiation, angiogenesis, chemoresistance, migration, invasion, epithelial-mesenchymal transition (EMT), and metastasis." (PMID 31510045, 2019).
tumor (continued). "In PC agents, we not only took into account of the androgen-independent pathway (triggered by EGF and WNT5A), but also DHT-mediated androgen-dependent signaling to determine the internal factors-associated tumor cell proliferation." (PMID 31504033, 2019). "Delivered wnt5a enhances tumor invasion by leading to the activation of β-catenin-independent Wnt signaling." (PMID 31686989, 2019). "The participation of Wnt5a in several inflammatory diseases is well known, but its role in tumor-promoting inflammation has been scarcely and fragmentarily studied." (PMID 31510045, 2019). "Wnt5a is considered to have a tumor-suppressive function in neuroblastoma, leukemia, ductal breast carcinomas, ER-positive breast cancer, colorectal cancer, and thyroid cancer." (PMID 31510045, 2019). "For example, TAM-derived exosomes enhance tumor invasion by delivering wnt5a in macrophages to breast cancer cells." (PMID 31686989, 2019). "Altogether these results indicate that miR-129-5p overexpression inhibits tumour growth and angiogenesis in vivo through the downregulation of Wnt5a." (PMID 29531296, 2018). "WNT5A is an auto- and paracrine β-catenin-independent ligand that has been shown to induce tumor suppression as well as oncogenic signaling, depending upon cancer type." (PMID 30171384, 2018). "In contrast, Wnt5a is a tumor suppressor in colorectal cancer, thyroid cancer, liver cancer, and malignant lymphoma." (PMID 29765514, 2018). "5-Aza-CdR treatment reversed the methylation status of the promoter and restored Wnt5a gene expression, which behaved as a tumor suppressor." (PMID 30079293, 2018). "Consistently, CD44, OAS3, ISG15, STAT1, and WNT5A were significantly upregulated whereas KIT was significantly downregulated in tumor compared to normal in GSE13861." (PMID 30134903, 2018). "In samples with WNT5A-positive macrophages, such cells only constituted 5–15% of the total number of macrophages in the tumor tissue." (PMID 30171384, 2018). "Previous studies have demonstrated that ectopic treatment with commercially available full-length recombinant WNT5A (rWNT5A) can elucidate both an oncogenic and a tumor-suppressive role of WNT5A depending on the cancer type." (PMID 30171384, 2018). "Consistent with in vitro experiments, BBR downregulated HNF4α, WNT5A, and cytoplasmic β-catenin expression in somatic tumor tissues, the same effect as knocking out HNF4α gene." (PMID 30405404, 2018). "Wnt5a methylation also differs among tumors, and the mechanism of Wnt5a methylation in tumor occurrence and development differs." (PMID 30079293, 2018). "To this point, we have only discussed the role of tumor cell-derived WNT5A; however, there is a very interesting study revealing a role of paracrine WNT5A signaling leading to a reduced number of tumor-initiating cells (TIC)." (PMID 30171384, 2018). "Understanding the signaling mechanism behind Wnt5a driven tumor progression and metastasis is imperative if we aim to create novel therapies against this pathway and to achieve our goal of increasing cancer patient survival." (PMID 29648538, 2018). "In patients, increased Wnt5a expression is known to correlate with increased tumor grade and metastasis." (PMID 29648538, 2018). "The data we present offers insights to the Wnt5a signaling pathway and its contribution to tumor progression and metastasis." (PMID 29648538, 2018). "In vitro studies with various cancer cell lines and tumor specimens from patients have revealed elevated expression of Wnt proteins (e.g., Wnt5a) and deregulated Wnt signal transduction pathways." (PMID 29371911, 2017). "We used virally-encoded shRNAs targeting either WNT2 or WNT5A to deplete these genes in CAF cells and then mixed CAF cells with HCT116-eGFP cells to create WNT-negative tumor:CAF spheroids." (PMID 29245949, 2017). "Wnt5a is known to promote cell migration by modulating several proteins of the cytoskeleton, providing tumor cells with abilities in relocation." (PMID 28320399, 2017).
tumor (continued). "Immunohistochemical analysis revealed a statis-tically significant correlation between Wnt5a protein expression and tumor grade (Sig." (PMID 28427201, 2017). "Conversely, Wnt5a was shown to inhibit tumor cell proliferation in brain, breast, and thyroid cancers." (PMID 28859077, 2017). "Next, transcript levels of Wnt5a isoforms in CRC tissues were further investigated in the first group of CRC tumor tissues (n = 68)." (PMID 28859077, 2017). "The elevated expression of Wnt proteins (e.g., Wnt5a) in tumor samples correlates with advanced stages and poor prognosis in solid tumors as well as hematological malignancies." (PMID 29371911, 2017). "There are several intracellular signaling pathways and adhesion molecules through which WNT5A has been shown to regulate migration and invasion of tumor cells." (PMID 28886116, 2017). "For assessing the effects of Wnt5a on tumor growth and metastasis in vivo, A549 cells transfected with sh-Wnt5a were subcutaneously or orthotopically injected into nude mice." (PMID 29054966, 2017). "The animal experimental results showed that sh-Wnt5a significantly increased tumor volume and tumor weight in A549 tumor-bearing mice as compared with the control." (PMID 29054966, 2017). "An enforced expression of Wnt5a led to a degradation of β-catenin and a reduced expression of Cyclin D1 and capacity of colony formation, indicating that Wnt5a acted as a tumor suppressor role in CRC by suppressing the canonical Wnt signaling pathway." (PMID 27895670, 2016). "With respect to its antitumor activity, Wnt5a is able to inhibit tumor invasion and metastasis by antagonizing the Wnt/β-catenin signaling pathway and inducing the degradation of β-catenin." (PMID 27895670, 2016). "As these initial studies demonstrate that Wnt5a can either induce or inhibit tumor progression through regulating cellular senescence, additional studies on the role of Wnt5a in senescence are needed in other cancers." (PMID 27571105, 2016). "In these malignancies, Wnt5a acted as a tumor suppressor mainly via antagonizing carcinogenetic Wnt/β-catenin pathway." (PMID 27608847, 2016). "Wnt5a was specifically selected as its up-regulation is characteristic to SCC tumors distinguishing the tumor microenvironment of SCC from AC." (PMID 27876017, 2016). "PTL tumor tissues showed Wnt5a+ and Ror2+ staining in 12 (54.5 %) and 18 (81.8 %) cases, respectively." (PMID 26608372, 2016). "Together these data support a role for Wnt5a in tumor cell migration, through activation of distinct signaling pathways." (PMID 27571105, 2016). "Apparently, WNT5A plays distinct functions in different tumor types, at different tumor stages, and likely in tumors with particular molecular characteristics." (PMID 26978652, 2016). "A higher expression of Wnt5a was also found in tumor tissues of smokers relative to matched normal tissues." (PMID 27895670, 2016). "MMTV-PyMT/Wnt5a-/- tumors also exhibited increased SIRT7 expression distributed throughout the tumor compared to those derived from MMTV-PyMT/Wnt5a+/+ mice." (PMID 27500936, 2016). "Together these studies suggest that Wnt5a signaling modulates the interaction between cancer cells and cells of the tumor microenvironment, contributing to disease progression." (PMID 27571105, 2016). "Tumor cell-derived Wnt5a has been demonstrated to play a dual role in human cancer initiation and progression." (PMID 27608847, 2016). "Wnt5a was also found to play a critical role in the interaction between tumor cells and the tumor microenvironment." (PMID 27571105, 2016). "Both methylation of Wnt antagonists (thereby interfering with their suppressive function) and of the Wnt5a promoter (resulting in low levels of Wnt5a, which acts a tumor suppressor) have been found." (PMID 27571104, 2016).
tumor (continued). "A more detailed understanding of the complex cross-talk between Wnt5a, its receptors and co-receptors in the tumor microenvironment will enable the development of inhibitors to block aberrant signaling and thereby favorably impact patient survival." (PMID 27571105, 2016). "Fzd5 expression in macrophages also indicates that Wnt5a from other cells, such as tumor cells, can exert effects on macrophages in a paracrinal manner." (PMID 27608847, 2016). "The interesting ability alternation of Wnt5a signaling between tumor suppressor genes and oncogenes has been exhibited in different cell types and tumors." (PMID 26608372, 2016). "Ectopic expression of WNT-5A led to reduction in β-catenin signaling and inhibition of clonogenicity and motility in ESCC cell lines suggesting the tumor suppressive role of WNT-5A in ESCC." (PMID 26514730, 2016). "Overexpression of Wnt5a, which belongs to Wnt family that encodes signaling glycoproteins, promotes invasion of NSCLC during tumor progression." (PMID 27610375, 2016). "The exact role played by Wnt5a in cancer remains controversial, as it shows both tumor-suppressing and oncogenic effects in different cancer types." (PMID 27571105, 2016). "The aberrant activation or inhibition of Wnt5a signaling is emerging as an important event in tumorigenesis, exerting both oncogenic and tumor suppressive effects." (PMID 27571105, 2016). "VEGF-A, WNT5A and TGFβ1 were upregulated by ERRα in tumor cells and all of these factors also significantly and positively correlated with ERRα expression in CRPC patient specimens." (PMID 27776343, 2016). "While Wnt5a expression contributes to tumor aggressiveness by inducing cancer cell invasion and metastasis, it can also enhance cell proliferation in some types of cancer." (PMID 27571105, 2016). "It is well known that Wnt5a has ample opportunities to influence diverse cell signaling, resulting in functional promiscuity on tumor initiation and progression." (PMID 25779663, 2015). "When we assessed the tumor-suppressive effect of Wnt5a on HeLa cells in anchorage-dependent tumor growth assays, we found that tumor growth was suppressed in the control cells, but such suppression was lost in cells depleted of endogenous Daple." (PMID 26126266, 2015). "WNT5A was also described as a potential tumor suppressor gene, able to prevent and reverse tumor genesis." (PMID 26316480, 2015). "Multivariate analysis further demonstrated that ROR2 expression (P < 0.001), Wnt5a expression (P = 0.003) and tumor TNM stage (P = 0.002) were independent prognostic factors." (PMID 26305508, 2015). "Third, the IHC data is semiquantitative, additional methods are needed to evaluate and confirm the expression level of ROR2 and Wnt5a in tumor cells." (PMID 26305508, 2015). "Xenograft tumor formation was reduced by Wnt5a depletion, and Ki67 (a cell proliferation marker) expression levels were also reduced in Wnt5a-depleted tumor cells." (PMID 25622531, 2015). "We suggest that, by affecting the exocytosis of numerous secreted factors in sensitive systems such as the cell rich microenvironment of a tumor, WNT5A signaling can have a much wider biological consequence than has previously been described." (PMID 24766647, 2014). "In doing so, we found that Wnt5a suppresses MMTV-Wnt1-induced tumor formation and redirects the tumors that form to a less basal-like phenotype as measured by reduced expression of keratin 5 (K5) and keratin 6 (K6)." (PMID 25401739, 2014). "Wnt3a and wnt5a expression had a concordance rate higher than 60% with a high concordance rate between the primary tumor and metastatic site." (PMID 24564183, 2014). "One of the most significant findings of this study is that Wnt5a suppresses tumor formation induced by high Wnt/β-catenin signaling." (PMID 25401739, 2014). "Even though Wnt5a was capable of antagonizing canonical Wnt signaling, we were not able detect reduced canonical Wnt signaling by Wnt5a in the non-tumor tissue in vivo." (PMID 25401739, 2014).
tumor (continued). "ROR2 is tyrosine-kinase receptor that plays an important role in developmental morphogenesis and in our network it was activated by the tumor-secreted WNT5A, a WNT pathway signaling mediator." (PMID 24597571, 2014). "Similar to BIN-1, COX2, and TβRIII above, this work implicates Wnt5a as a factor with dual roles in carcinogenesis including tumor invasion and metastasis, as well as the suppression of local immune surveillance." (PMID 25339948, 2014). "Wnt5a is able to antagonize the canonical Wnt signaling pathway, promote the degradation of β-catenin and inhibit tumor invasion and metastasis." (PMID 24944588, 2014). "Wnt5a plays a variety of roles in different types of tumors, depending on the binding receptors, downstream effectors, exogenous inhibitors, tumor microenvironments and the extracellular matrix, particularly the cell/tissue-tropic contexts." (PMID 24944588, 2014). "Enhanced Wnt5A was detected in the tumour biopsies, and significantly elevated Wnt5A and/or ABCB1 expression was shown in biopsied samples after chemotherapy." (PMID 25401518, 2014). "Wnt5a clearly enhances the migration of DFSCs as we discovered here, consistent with Wnt5a promotion of tumor cell migration." (PMID 25510849, 2014). "When tumors were collected after 21 days of doxorubicin treatment, reduced tumor sizes from the Wnt5A-knockdown groups were observed (Figure." (PMID 25401518, 2014). "The data demonstrated tumor regression in the Wnt5A-knockdown tumor treated with doxorubicin, suggesting that this Wnt5A-related pathway contributes to MDR tumor progression." (PMID 25401518, 2014). "In non-tumor tissues, over-expression of Wnt5a in MMTV-Wnt1 mammary glands resulted in attenuation of phenotypes normally observed in MMTV-Wnt1 glands including hyperbranching and increased progenitor and basal cell populations." (PMID 25401739, 2014). "The data demonstrate that Wnt5a suppresses tumor formation and promotes a phenotypic shift in MMTV-Wnt1 tumors." (PMID 25401739, 2014). "Taken together, the current study demonstrated that Wnt5a was overexpressed in human NSCLC tissues and closely associated with tumor angiogenesis." (PMID 24999479, 2014). "Other studies suggest that Wnt5a can promote tumor progression; therefore, the effects of Wnt5a are likely dependent on the context." (PMID 25401739, 2014). "As such, direct in vivo demonstration of Wnt5a effects in vivo would be informative in establishing a role for Wnt5a as a tumor suppressor and in elucidating specific mechanisms of action." (PMID 25401739, 2014). "Among the relapsed patients, 19 of the 24 (79%, P<0.001) of the biopsied samples showed significant increases of Wnt5A expression, and 21/24 (88%, P<0.001) of the tumor biopsies also showed a significant upregulated ABCB1 expression after chemotherapy." (PMID 25401518, 2014). "Emerging data suggest that the tumor-mediated expression of Wnt5a contributes to the generation of an immunotolerant microenvironment." (PMID 25339948, 2014). "Consistently, the knockdown of WNT5A by shRNA1 significantly enhanced the tumor growth of PIAS1 knockdown MDA-MB231 cells in vivo." (PMID 24586797, 2014). "Analysis of non-tumor tissue demonstrated that expression of Wnt5a attenuated some of the effects of Wnt1 on the mammary gland including increased side branching and increased progenitor and basal cell populations." (PMID 25401739, 2014). "To begin to understand the mechanism of how Wnt5a inhibited tumor formation, we compared non-tumor tissue from MMTV-Wnt1 and MMTV-Wnt1;Wnt5a mice." (PMID 25401739, 2014). "A tumor tissue array was constructed and 361 samples were evaluated for Wnt-5a reactivity by immunohistochemistry." (PMID 23990917, 2013). "Down-regulation of any of these genes by WNT5A would be expected to contribute to inhibition of tumor progression." (PMID 23484019, 2013).